DAZ3 (deleted in azoospermia 3)
Description:
RNA-binding protein that plays an essential role in spermatogenesis. May act by binding to the 3'-UTR of mRNAs and regulating their translation.
Synonyms: pDP1679
Tractability: PROTAC: ubiquitination databases record sites on it.
Gene: Protein-coding gene on chromosome Y (24,763,069 to 24,813,492, reverse strand). Ensembl gene ENSG00000187191.
Subcellular location: Cytoplasm; Nucleus
Gene Ontology:
Molecular function: protein binding; translation activator activity; mRNA 3'-UTR binding; nucleic acid binding; RNA binding
Biological process: 3'-UTR-mediated mRNA stabilization; positive regulation of translational initiation
Cellular component: cytoplasm; protein-containing complex; nucleus
Homologues: Orthologues: dog DAZL (41% identical), guinea pig DAZL (38% identical), tropical clawed frog dazl (27% identical), zebrafish dazl (19% identical), Caenorhabditis elegans daz-1 (16% identical), Drosophila melanogaster bol (13% identical). Paralogues in human: DAZ2 (99% identical), DAZ4 (99% identical), DAZ1 (92% identical), DAZL (41% identical), BOLL (17% identical).
Diseases named in the same sentence as DAZ3 in open-access papers:
DAZ3 is named in the same sentence as 4 diseases in open-access papers, as found by Europe PMC text mining. Sharing a sentence is not in itself a finding about the gene and the disease. The quoted sentences say what the papers report.
infertile (3 papers, 2019 to 2025). "Some infertility-related genes were identified in these networks, including DAZ family genes (DAZ1, DAZ3, and DAZ4), NF1 family TF motifs (NFIX), and ras association domain family 8 (RASSF8)." (PMID 40391511, 2025). "The remaining 12 out of 50 infertile men (1.2%) and 3 out of 9 controls (0.5%) identified as gr/gr with the removal of sY1291, DAZ cluster II (DAZ3 + 4) and a copy of CDY1a show the r2/r4 NAHR pattern (Fig. 1FIII)." (PMID 31000748, 2019).
male infertility (3 papers, 2023 to 2025). The inability of the male to effect fertilization of an ovum after a specified period of unprotected intercourse. "The loss of the deleted in azoospermia (DAZ) genes DAZ1, DAZ3, and DAZ4 leads to spermatogenic arrest, contributing to male infertility." (PMID 40391511, 2025). "Moreover, we investigate the Y-chromosome genes, DAZ1/DAZ2/DAZ3/DAZ4, of which structural variants have been linked to male infertility, and X-chromosome genes OPN1LW and OPN1MW linked to eye disorders." (PMID 37365340, 2023).
DAZ3 also shares sentences with these, for which no sentence is quoted: Azoospermia (2 papers); schizophrenia (1).